RN7SKP9 (RN7SK pseudogene 9)
Gene: Miscellaneous RNA gene on chromosome 13 (99,205,708 to 99,206,006, forward strand). Ensembl gene ENSG00000201793.
Homologues: Orthologues: chimpanzee 7SK (97% identical). Paralogues in human: 7SK (83% identical), RN7SKP176 (83% identical), RN7SKP180 (83% identical), RN7SKP133 (82% identical), RN7SKP255 (82% identical), RN7SKP203 (82% identical), RN7SKP79 (81% identical), RN7SKP217 (80% identical), RN7SKP25 (80% identical), RN7SKP44 (80% identical), RN7SKP124 (80% identical), RN7SKP189 (80% identical), and 283 more.